IL10 (interleukin 10)
Diseases named in the same sentence as IL10 in open-access papers (continued):
Sharing a sentence is not in itself a finding about the gene and the disease.
Arthritis (continued). "The results show that GMSC‐Exo has the same or stronger effects compared with GMSC in inhibiting IL‐17A and promoting IL‐10, reducing incidences and bone erosion of arthritis, via inhibiting IL‐17RA‐Act1‐TRAF6‐NF‐κB signal pathway." (PMID 34953015, 2022). "The dysregulation of IL-10 has been reported in various inflammatory diseases such as lupus, arthritis, and psoriasis." (PMID 35185845, 2022). "We demonstrated the anti-arthritogenic properties of IL-10-edited human AMMs in experimental arthritis." (PMID 35887258, 2022). "Consistent with previous reports, we found that AMM/I administration downregulated Th17 cells, suggesting arthritis suppression by IL-10 derived from AMM/I." (PMID 35887258, 2022). "IL-10 producing Bregs are able to stop arthritis progression and thus have an anti-inflammatory effect in CIA, which has been reported in several publications." (PMID 36009497, 2022). "For instance, polymeric proanthocyanidin preparation from Serjania schiedeana was shown to reduce joint inflammation and increase the levels of the anti-inflammatory type-2 cytokines IL-4 and IL-10 in the joint and spleen in experimentally induced arthritis." (PMID 36551801, 2022). "In this study, we investigated the anti-arthritogenic properties of genome-edited IL-10-overexpressing human amniotic MSCs (AMM/I) in cartilage-damaged experimental arthritis." (PMID 35887258, 2022). "In the DBA/1 mouse line, heterozygous (IL-10±) and homozygous (IL-10−/−) mice develop worse arthritis compared to wildtype (WT) mice following induction of collagen type II." (PMID 36173485, 2022). "In the early 2000s, Mauri and colleagues demonstrated IL-10-producing B cells were also able to suppress experimental arthritis." (PMID 36179248, 2022). "Suppression of IL-10 in synovial cells increases the levels of inflammatory cytokines, and systemic treatment with IL-10 suppresses the development of arthritis." (PMID 35887258, 2022). "The results showed that GMSC‐Exo have the same or even more immunoregulatory effects compared with GMSC in some aspects, such as promoting the secretion of IL‐10, inhibiting that of IL‐17A, and reducing the incidence of arthritis and bone erosion." (PMID 34953015, 2022). "Our results suggest that IL-10-promoting signaling pathways, especially in established arthritis, are strengthend via β2-ADR mechanisms." (PMID 36009497, 2022). "Research on this inhibitor is somewhat limited to date but has included studies of its effect on bone resorption and osteoporosis, arthritis, and the production of Th2 cells and cytokine IL-10 in pregnant mice." (PMID 36073547, 2022). "We measured CXCL1, CXCL5 IL-6, IL-8, IL-10, TNFα, and total IgG levels in the aliquots of set 1 and set 2 in eight arthritis patients." (PMID 34998422, 2022). "This claim is corroborated by studies conducted on animal models of arthritis, which revealed the role of IL‐10 in the reduction of arthritis severity." (PMID 35894711, 2022). "Some findings indicated more severe arthritis in TLR2−/− mice than wild-type (WT) controls and that TLR2−/− mice promote the effector phase of arthritis through decreased IL-10 production by macrophages." (PMID 35241180, 2022). "Lowering the clinical degree of experimental arthritis by lactobacilli administration was IL-10 dependent as well." (PMID 35626660, 2022). "Phlomisoside F (5, 10, and 20 mg/kg, p.o., for 28 days) inhibited the expression of TNF-α, IL-1β, IL-6, COX-2, and 5-lipoxygenase (5-LOX), and increased the expression of IL-10 in complete Freund's adjuvant-induced arthritis male Wistar rats." (PMID 35368757, 2022). "In mouse models of RA, administration of neutralizing anti-IL-10 antibodies showed an acceleration of arthritis, while intraarticular overexpression of IL-10 diminished synovitis and cartilage proteoglycan depletion." (PMID 34680530, 2021).
Arthritis (continued). "This is supported by the fact that mice with AhR deletion developed exacerbated arthritis accompanied by reduced IL-10-producing CD19+CD21hiCD24hiBregs." (PMID 33841422, 2021). "Mice with IL-10 knocked-out in B cells developed exacerbated arthritis accompanied by increased antibodies and inflammatory Th1 and Th17 cells, suggesting the important role of IL-10 in B cell-mediated immune regulation." (PMID 33841422, 2021). "These regulatory B cells (Bregs) cells also produce IL-10 themselves and their passive transfer provides significant protection from arthritis to the mice." (PMID 33717145, 2021). "IL-10–producing B cells induced by acetate were functional and decreased arthritis severity when adoptively transferred." (PMID 33729999, 2021). "Mice that received AAV8.CII prophylaxis had an approximate 50% reduction in the OD of pro-inflammatory IFNγ and a concomitant 2.5-fold increase in IL-10 level when compared to arthritis controls." (PMID 34521922, 2021). "IL-10 and IL-35 cytokines have been reported to regulate arthritis pathogenesis and attenuate inflammatory joint symptoms." (PMID 33707483, 2021). "HIF-1α drives IL-10 expression in B-cells in controlling autoimmune inflammation such as arthritis and experimental autoimmune encephalomyelitis." (PMID 33519819, 2020). "Tolerance to HSP65 and arthritis prevention induced by the recombinant L. lactis was associated with increase in IL-10 production by B cells and it was dependent on LAP+ T cells, IL-10 and TLR2 signaling." (PMID 33072101, 2020). "This was demonstrated by injection of ACs into collagen-induced arthritis model, which induced the production of IL-10 by Breg cells, a process that alleviates inflammation." (PMID 32973780, 2020). "IL-10-producing CD1dhiCD5+ B cells, also defined as B10 cells, play an inhibitory role in arthritis development." (PMID 33072104, 2020). "Synovial cells from patients with arthritis that were incubated with M. tuberculosis HSP70 led to increased production of IL-10." (PMID 33348708, 2020). "One proposed mechanism of action shows that ingested HA binds to Toll-like receptor-4 and promotes the expressions of interleukin-10 and cytokine signalling, which both lead to anti-inflammation of arthritis." (PMID 32650511, 2020). "A previous study analyzing macrophage subsets in human arthritis found M1 polarization predominating in RA and IL-10-expressing macrophages in SpA, including PsA." (PMID 33679701, 2020). "Exosomes derived from IL-10-stimulated dendritic cells have been observed to suppress collagen-induced arthritis in mice and reduce the clinical severity of established arthritis." (PMID 32993051, 2020). "Studies have shown the importance of IL-4 and IL-10 in the control of arthritis because blocking these cytokines has resulted in the accelerated onset of CIA." (PMID 30959746, 2019). "In an animal model of RA, chimeric mice lacking the B cells producing IL-10 developed severe collagen-induced arthritis with greatly decreased IL-10-secreting CD4 Treg cells and increased Th1 and Th17 cells." (PMID 31554310, 2019). "In this regard, it has been reported that SOCS3 is the key mediator of the inhibitory effects of IL-10 in macrophages stimulated with LPS, and in an in vivo model of collagen induced arthritis." (PMID 31214200, 2019). "Administration of RvD5n-3 DPA to arthritic P. gingivalis–inoculated mice increased intestinal Il-10 expression, restored gut barrier function, and reduced joint inflammation." (PMID 31292292, 2019). "In our model, suppression of arthritis following α-GalCer was IL-10 independent as there was equivalent suppression of the disease in α-GalCer-treated Il10ra−/− and WT mice." (PMID 29449556, 2018). "Our previous report showed that combined treatment of low-dose IL-18 with IL-10 can prevent the progression of arthritis in CIA mice and that this is mediated by a GATA-3-dependent mechanism." (PMID 29854762, 2018).
Arthritis (continued). "IL-10 has been shown to contribute to the prevention of arthritic inflammation in macrophages during collagen-induced arthritis development." (PMID 30648118, 2018). "Nevertheless, other teams have reported the induction of IL-10-dependent Treg after the prophylactic infusion of apoptotic cells in arthritis models." (PMID 29062314, 2017). "For example, while the transfer of IL-10-producing Bregs drives Treg cell expansion and modulates arthritis in mice, treatment of SLE patients with IL-10-specific monoclonal antibodies ameliorates disease." (PMID 28456914, 2017). "It was evidenced that in vivo administration of agonistic anti-CD40 antibodies resulted in the augmentation of Bregs subset providing IL-10 and amelioration or prevention of arthritis via inhibition of the Th1 response." (PMID 28477096, 2017). "Experimental models of collagen-induced arthritis revealed that recombinant IL-10 decreases the incidence, delays the onset, and reduces the severity of arthritis." (PMID 28257625, 2017). "In this study using the collagen-induced arthritis (CIA) murine model, IL-10-treated DC-derived exosomes were able to suppress the onset of arthritis and reduce the severity of established arthritis." (PMID 28441721, 2017). "Further, up-regulation of SOCS1 and/or 3 in CIA coincided with increased IL-10 production and reduced severity of arthritis." (PMID 27159398, 2016). "Next, these data reveal, interestingly, arthritis induction promotes extra-articular changes in mobility and anxiety in Il10-/- mice." (PMID 37220589, 2016). "Treatment with Th2 cytokines (IL-4, IL-10, and IL-13) was tested in many animal models of arthritis based on the Th1 bias of T cells, showing considerable promise." (PMID 27579330, 2016). "Studies addressing the role of TGF-β and IL-10 in experimental arthritis have shown variable results." (PMID 28057980, 2016). "Our results suggest that the inhibition of arthritis in RORγt Tg mice was mediated by suppressor cell subsets, including IL-10 producing CCR6+RORγt+Foxp3+ Treg cells." (PMID 25928901, 2015). "Arthritis severity for B6, Mir155-/-, Il10-/-, and DKO mice was determined by swelling of rear ankles and by histopathology scoring." (PMID 26252010, 2015). "B6 mice developed mild arthritis, and Il10-/- mice developed more severe arthritis, as measured by ankle swelling and histopathology scoring, as has been reported previously." (PMID 26252010, 2015). "Examination of the paws revealed reduced mRNA for STAT1 but increased mRNA for IL-10, an immunomodulatory cytokine for arthritis." (PMID 25561237, 2014). "We wanted to evaluate if the increased IL-10 responses seen with the protective function of IL-22 was blunted or reversed during arthritis." (PMID 24676270, 2014). "The arthritis observed in C57BL/6 mice is modulated by the production of IL-10 from CD4+ T cells and macrophages." (PMID 24904837, 2014). "Here, we show that IL-10 negatively regulates the expression of NLRP3 inflammasome components within the inflamed synovium of experimental arthritis and provide a link to degenerative bone erosion." (PMID 25175678, 2014). "This increased arthritis severity with accompanying decreases in bacterial burden is also observed in the B6 IL10−/− mouse model of arthritis, and is believed to be due primarily to enhanced innate immune responses." (PMID 24967703, 2014). "Other gene knockout and cytokine blocking studies have shown tissue-specific effects of IL-10 and chemokines on arthritis and carditis severity." (PMID 24967703, 2014). "Recombinant IL-22 restrains progression of arthritis via increase in IL-10 responses when administered prior to onset of arthritis." (PMID 24676270, 2014). "In experimental models of arthritis, leptin deficient mice showed a milder form of antigen-induced arthritis associated with the reduction of IFN-γ production and the increase in IL-10 secretion by in vitro reactivated lymph node cells." (PMID 24799765, 2014).
Arthritis (continued). "In our previous report administration of recombinant IL-22 prior to onset of joint inflammation increased IL-10 responses and restrained the progression of arthritis." (PMID 24676270, 2014). "Whereas the C57BL/6 (B6) mouse strain develops mild arthritis, C3H and various knockout strains such as B6 IL10−/− mice develop moderate to severe arthritis." (PMID 24967703, 2014). "In our previous study we reported that administration of recombinant IL-22 prior to the onset of arthritis reduces the severity of subsequent arthritis via increase in IL-10, implying a possible protective role of IL-22 during this phase." (PMID 24676270, 2014). "Another study found that administration of anti-IL-10 monoclonal antibody (21 consecutive days) to six patients with moderate lupus (an open study) resulted in healing of arthritis and cutaneous lesions." (PMID 24629023, 2014). "Daily administration of green tea extracts in drinking water slowed progression of arthritis in rat adjuvant-induced arthritis, inhibited serum levels of IL-17, and increased serum levels of IL-10." (PMID 24284399, 2013). "Particularly, we have shown that immunocytokines consisting of the L19 antibody or the F8 antibody (serving as delivery vehicle) and of human IL-10 were able to inhibit arthritis progression in the murine model of collagen-induced arthritis." (PMID 24289726, 2013). "The most prominent example is represented by recombinant human IL-10, which has shown activity in the collagen-induced model of arthritis and which has been investigated in controlled clinical studies." (PMID 24289726, 2013). "It is also interesting to note that in the arthritis-induced animals treated with prasugrel, the plasma levels of IL-10 were significantly decreased." (PMID 23861957, 2013). "For example, SOCS-3 has been reported as a key mediator in the inhibitory effects of IL-10 in macrophages stimulated with LPS and in an in vivo model of collagen-induced arthritis." (PMID 24260222, 2013). "Several subsets of IL-10(+)CD19(+) B cells have been intensively reported as immune-suppressors in other diseases including arthritis, experimental autoimmune encephalomyelitis." (PMID 23724100, 2013). "Agonistic monoclonal antibodies to CD40 reduced collagen-induced arthritis, possibly through upregulation of IL-10 and to lesser extent IL-4, indicating an anti-inflammatory role in addition to the pro-inflammatory role of CD40." (PMID 23300544, 2012). "These increased inflammatory conditions result in exacerbated arthritis in IL-10-/- B cell mice as compared to WT B cell mice." (PMID 22315945, 2012). "IL-10-/- B cell mice have an exacerbated AIA arthritis phenotype, including increased clinical scores and knee swelling, enhanced Th17 and Th1 development and a reduction in regulatory T cells." (PMID 22315945, 2012). "A precise and restricted increase in IL-10, produced by B cells and other APCs, ameliorates the course and severity of arthritis." (PMID 23166758, 2012). "In experimental arthritis, we have shown that the transfer of the main producers of IL-10, namely CD19+CD21hiCD23hiCD1dhi transitional 2 marginal zone precursor B cells (T2-MZP), prevents or ameliorates established disease." (PMID 22315945, 2012). "Taken together, our study demonstrates that disease-regulated therapy mediated by IL-10 has a beneficial outcome on arthritis development in CIA and provides a step towards disease-regulated therapies in human autoimmune arthritis." (PMID 23166758, 2012). "The antiinflammatory cytokine IL-10 plays an important role for control of excessive immunity and damage to the host during infections, and we showed that IL-10 is protective against S. aureus arthritis, at least partly by inhibition of TNF-α." (PMID 22507741, 2012). "These conditions result in exacerbated experimental arthritis in IL-10-/- B cell mice as compared to WT B cell mice." (PMID 22315945, 2012).
Arthritis (continued). "Our data are supported by those of others, where it was recently found that a local and inflammation-dependent increase in IL-10 produced by endothelial cells results in suppressed development of zymosan induced arthritis in mice." (PMID 23166758, 2012). "To explore this concept we expressed the immunoregulatory cytokine interleukin (IL)-10 gene under the control of an inflammation dependent promoter in a mouse model of RA - collagen type II (CII) induced arthritis (CIA)." (PMID 23166758, 2012). "The cytokine IL-10 appears to play a partial role in the A12 prevention of arthritis, whereas IL-4 is more potent." (PMID 22569209, 2012). "IL-10 is known to be a potent anti-inflammatory cytokine, and indeed, its production was found in the prior study to prevent arthritis." (PMID 23304456, 2012). "Using intracellular cytokine staining it was demonstrated that the IL-10-/- B cell mice with arthritis had an increased CD4+ IFNγ producing population." (PMID 22315945, 2012). "To investigate the link between increased IL-10 production and suppression of arthritis we determined the mRNA levels of the suppressors of cytokine signalling 1 and 3 (SOCS1 and SOCS3)." (PMID 23166758, 2012). "Nevertheless, in both an acute inflammatory model and a systemic experimental arthritis, IL-10-/- B cell mice have an exacerbated arthritis phenotype." (PMID 22315945, 2012). "We found that this promoter, driving the IL-10 gene expression, does not induce increased systemic (serum) levels of IL-10 during the course of arthritis in vivo, but a locally increased IL-10 expression in lymph nodes; particularly in B cells and other APCs." (PMID 23166758, 2012). "IL-10 signaling in T cells is critical for dampening the pathogenesis of collagen-induced arthritis by maintaining the function of Tregs and the recruitment of IL-17+γδ T cells." (PMID 22192790, 2011). "More recently, in a proteoglycan-induced arthritis model, TBHsp70 immunization showed a protective potential that was dependent on IL-10." (PMID 21170379, 2010). "Many of the expected cytokines are raised during arthritis in this model, such as IL-1β, IL-10 and IL-6, however, unexpectedly both GM-CSF and TNFα remain low." (PMID 21073728, 2010). "We have demonstrated that TBHsp70 induces IL-10 production by monocytes and synovial cells of arthritis patients, leading to a reduction of TNF-α e IFN-γ levels." (PMID 21170379, 2010). "IL10 is a particularly attractive anti-inflammatory cytokine for arthritis treatment, which has exhibited an excellent tolerability profile in rodents, monkeys and patients at doses up to 25 μg/kg." (PMID 19781067, 2009). "It was recently shown that mycobacterial HSP70 treatment in vitro induced IL-10 production in monocytes from blood and synovial tissue from arthritis patients." (PMID 18410682, 2008). "Immunization with mycobacterial HSP70 has been found to protect rats from experimentally induced arthritis through induction of IL-10 producing T cells." (PMID 18410682, 2008). "In various animal models of arthritis, IL-10 reduced joint swelling, cellular infiltration, cytokine production, and cartilage degradation when administered to animals either before or after induction of disease." (PMID 16859503, 2006). "In the collagen type II-induced arthritis model of mice, chemical sympathectomy before the induction of arthritis decreased disease severity and induced the expression of IL-4 and IL-10." (PMID 16889669, 2006). "The role of IL-10 in arthritis clearly seems a protective one, as indicated by studies on the amelioration of collagen-induced arthritis by administration of IL-10 or its augmentation in IL-10 knockout mice." (PMID 15899031, 2005). "In contrast, we did not observe any association between high IL‐10 levels and arthritis or myalgia in the present study." (PMID 41556482, 2026).